DLG1-AS1 (DLG1 antisense RNA 1)
Gene: Long non-coding RNA gene on chromosome 3 (197,298,225 to 197,309,307, forward strand). Ensembl gene ENSG00000227375.
Diseases named in the same sentence as DLG1-AS1 in open-access papers:
DLG1-AS1 is named in the same sentence as 1 disease in open-access papers, as found by Europe PMC text mining. Sharing a sentence is not in itself a finding about the gene and the disease. The quoted sentences say what the papers report.
cervical cancer (1 paper, 2021). A primary or metastatic malignant neoplasm involving the cervix. "DLG1 antisense RNA 1 (DLG1-AS1) has been identified as a novel oncogenic lncRNA in cervical cancer." (PMID 33407499, 2021). "DLG1 antisense RNA 1 (DLG1-AS1) has been found to be up-regulated in cervical cancer." (PMID 33407499, 2021).